CYP4F3 (cytochrome P450 family 4 subfamily F member 3)
Diseases named in the same sentence as CYP4F3 in open-access papers:
CYP4F3 is named in the same sentence as 82 diseases in open-access papers, as found by Europe PMC text mining. Sharing a sentence is not in itself a finding about the gene and the disease. The quoted sentences say what the papers report.
breast carcinoma (7 papers, 2010 to 2025). "The CYP4B1, CYP4F12, and CYP4F3 overall survival (OS) analyses were retrieved using the TIMER2.0 web server in breast cancer." (PMID 40723371, 2025). "Bioinformatics indicated that breast cancer is influenced by genes like CYP4B1, CYP4F12, and CYP4F3." (PMID 40723371, 2025). "On the other hand, breast cancer patients (n = 1100) with low CYP4B1 and CYP4F12 expression levels showed better cumulative survival, whereas patients with high CYP4F3 expression had better overall survival than their counterparts." (PMID 40723371, 2025). "Based on these findings, the upregulation of CYP4F3 and CYP4F8 in breast cancer can be confirmed along with their role in tumour progression as their overexpression was also identified in our study." (PMID 33991433, 2021). "This study emphasizes CYP4B1, CYP4F12, and CYP4F3 gene expression levels, presenting tumor versus normal tissue analysis, their expression adjusted by stages, their correlation with BRCA1, BRCA2, and ESR1, the estrogen receptor status, and the overall survival analysis in breast cancer patients." (PMID 40723371, 2025).
lung carcinoma (7 papers, 2020 to 2025). "Among 28 significant single-nucleotide polymorphisms (SNPs) identified after FDR correction, 26 were located within CYP4F3, with SNP rs4646904 showing a strong association with lung cancer risk (p = 8.65 × 10−6; FDR = 0.018)." (PMID 40723371, 2025). "A meta-analysis of six genome-wide association studies (GWAS) from the TRICL consortium identified CYP4F3 as a potential gene involved in lung cancer susceptibility." (PMID 40723371, 2025). "Although statistical significance diminished upon inclusion of the Harvard Lung Cancer Study cohort (p = 3.52 × 10−3), the findings suggested a possible role for CYP4F3 in lung cancer predisposition, particularly among smokers, warranting further functional investigation." (PMID 40723371, 2025). "Here, the CYP4F3 SNP rs4646904 G>A is significantly associated with a higher lung cancer risk." (PMID 40858268, 2025). "Yin and collaborators studied the potential role of the CYP4F3 gene locus in lung cancer." (PMID 40858268, 2025). "CYP4F3 has been identified as a cancer promoter of lung cancer." (PMID 36199579, 2022). "Cytochrome P450 family 4 subfamily F member 3 (CYP4F3) has been reported to have good diagnostic values for osteosarcoma, and a potentially functional SNP in CYP4F3 (rs4646904) may contribute to the etiology of lung cancer." (PMID 36212177, 2022). "The upregulated genes included CYP4F3, IL1RL1, PTGS2, and CXCL8, which are related to inflammation; HKDC1, MYEF2 and CYP1A1, which are related to hepatocarcinoma or lung carcinoma; and SLC7A11 and NEFM, which are related to neuronal damage." (PMID 33247188, 2020).
celiac disease (4 papers, 2010 to 2025). An autoimmune genetic disorder with an unknown pattern of inheritance that primarily affects the digestive tract. "A C5a receptor antagonist ameliorates pathology in this model, and genetic association studies link variants of the CYP4F2 and CYP4F3 genes with celiac disease in humans." (PMID 26613087, 2015). "Neutrophils and colonic mucosa from patients with inflammatory bowel disease have reduced LTB4 hydroxylase activity, and genetic association studies link variants of the CYP4F2 and CYP4F3 genes with celiac disease and Crohn's disease." (PMID 26613087, 2015). "Recent reports have shown the expression of CYP4F2 and CYP4F3 genes in the colon of patients with inflammatory celiac disease." (PMID 26114549, 2015).
steatosis (4 papers, 2009 to 2024). Increased lipid within the cytoplasm of cells. "CYP4F3 catalyzes the inactivation of the proinflammatory leukotriene B4 by ω-oxidation in human neutrophils, which explains the anti-inflammatory effects of AICAR in HFD-induced steatosis." (PMID 36834782, 2023).
colorectal cancer (3 papers, 2024 to 2025). A primary or metastatic malignant neoplasm that affects the colon or rectum. "Recent studies suggest a potential role of CYP4F3 in the progression of colorectal cancer." (PMID 40858268, 2025). "Thus, CYP4F3 could be a potential therapeutic target for colorectal cancer." (PMID 40858268, 2025).
prostate carcinoma (3 papers, 2021 to 2025). A carcinoma that arises from epithelial cells of the prostate gland. "Research has shown that androgens can significantly increase the expression of CYP4F2 and CYP4F3 through androgen receptor (AR) in prostate cancer cells, while PON1 activity is modulated by estrogen through HDL metabolism pathways." (PMID 40115349, 2025). "Prostate cancer patients with low CYP4F3 gene expression showed a decreased cumulative survival of about 35% at about 130 months, whereas endometrial cancer patients with high CYP4F3 gene expression levels depicted a decreased cumulative survival of about 50% at 120 months." (PMID 40723371, 2025). "Over expression of CYP4F3 and CYP4F8 was reported in several studies to regulate tumour progression and proliferation in various types of cancers such as breast and prostate cancer." (PMID 33991433, 2021).
cervical cancer (2 papers, 2022 to 2025). A primary or metastatic malignant neoplasm involving the cervix. "In the case of CYP4F3, the findings included its emergence as a progression marker in bladder cancer, modulated by calcitriol in cervical cancer; it was also associated with poor prognosis in colorectal liver metastasis and included in a prognostic model of endometrial cancer." (PMID 40723371, 2025).
Crohn disease (2 papers, 2022 to 2025). A gastrointestinal disorder characterized by chronic inflammation involving all layers of the intestinal wall, noncaseating granulomas affecting the intestinal wall and regional lymph nodes, and transmural fibrosis. "Children who consume a diet with a higher ratio of n-6:n-3 PUFA intake may be more susceptible to Crohn’s disease if they also carry SNPs in Cytochrome P450 Family 4 Subfamily F Member 3 (CYP4F3), Fatty Acid Desaturase 1 and 2 (FADS1, FADS2)." (PMID 35450067, 2022).
endometrial cancer (2 papers, 1997 to 2025). Primary or metastatic malignant neoplasm involving the endometrium (mucous membrane that lines the endometrial cavity). "An analysis of the TCGA dataset identified CYP4F3 as a component of a prognostic model in endometrial cancer, where elevated expression correlated with reduced overall survival." (PMID 40723371, 2025).
hepatic diseases (2 papers, 2022 to 2024). "In this nomogram, factors such as the number of liver metastases and chemotherapy history did not impact prognosis while extra hepatic diseases emerged as the most influential prognostic factor, followed by the risk factors identified in our model—the genes CYP4F3 and ATG7." (PMID 38795162, 2024).
metastasis (2 papers, 2017 to 2022). The spread or migration of cancer cells from one part of the body (where they first appeared) to another. "Moreover, we have validated some previously reported overexpressed genes such as TGFB1, IBSP, MMP9, or ITGB3 in bone metastasis; CRYAB, NRCAM, and SOX2 in brain metastasis; VEGF and IL6 in lung metastasis; and CYP4F3 in liver metastasis." (PMID 34051058, 2022).
abscess (1 paper, 2021). An inflammatory process characterized by the accumulation of pus within a newly formed tissue cavity which is the result of a bacterial, fungal, or parasitic infection or the presence of a foreign body. "Compared with the healthy control, significant upregulation in the gene expression of CYP4F3, VEGF, IL-8, TLR2 (P < 0.0001), and MMP-9 (P < 0.001) was found in the abscesses." (PMID 34539639, 2021). "In our study, the inhibition of CYP4F3 in abscess was not correlated to 17-octadecynoic acid, the most abundant metabolite significantly identified in the periapical abscess, perhaps due to the significant upregulation of CYP4F3." (PMID 34539639, 2021).
adrenocortical carcinoma (1 paper, 2025). "To date, no specific studies have established a direct association between CYP4F3 and adrenocortical carcinoma, either as a diagnostic biomarker or a prognostic indicator." (PMID 40723371, 2025). "According to data from the Human Protein Atlas, CYP4F3 shows no detectable expression in adrenocortical carcinoma, suggesting a limited role in the molecular profile of this malignancy." (PMID 40723371, 2025).
diabetes (1 paper, 2016). "For example, in subjects with prediabetes versus controls, cytochrome P450, family 4, subfamily F, polypeptide 3 (CYP4F3), CYP4F8, Phospholipase A2, group IIC (PLA2G2C), and PLA2G4E were differentially methylated, while in subjects with diabetes versus prediabetes, CYP2E1 and PLA2G12A were involved." (PMID 27555869, 2016).
esophageal cancer (1 paper, 2025). A primary or metastatic malignant neoplasm involving the esophagus. "According to available data from the Human Protein Atlas, CYP4F3 exhibits detectable transcript-level expression in esophageal cancer cell lines." (PMID 40723371, 2025). "Consequently, no prognostic association can currently be established for CYP4F3 in esophageal cancer." (PMID 40723371, 2025).
inflammatory bowel disease (1 paper, 2022). A spectrum of small and large bowel inflammatory diseases of unknown etiology. "CYP4F3 is associated with inflammatory diseases, like inflammatory bowel disease; however, the role of CYP4F3 in IPF is unknown." (PMID 36267568, 2022).
intraepithelial neoplasia (1 paper, 2024). A precancerous neoplastic process that affects the squamous, glandular, or transitional cell epithelium without evidence of invasion. "Similarly, immunostaining revealed that CYP4F3 expression was higher in patients’ tumor tissues compared to intraepithelial neoplasia and normal tissues." (PMID 39106550, 2024).
pancreatic ductal adenocarcinoma (1 paper, 2020). An infiltrating adenocarcinoma that arises from the epithelial cells of the pancreas. "In pancreatic ductal adenocarcinoma, CYP4F3, one isoform of the cytochrome P450 (CYP) superfamily, was shown to be upregulated in tumor tissues and could serve as a distinguishing marker." (PMID 32894095, 2020).
periapical abscess (1 paper, 2021). "CYP4F3, VEGF, MMP-9, IL-8, and TLR2 represented the most upregulated genes in periapical abscess." (PMID 34539639, 2021). "Significant higher expression of CYP4F3 (P < 0.0001), VEGF (P < 0.0001), MMP-9 (P < 0.001), IL-8 (P < 0.0001), and TLR2 (P < 0.0001) were noted in the periapical abscess compared with healthy controls." (PMID 34539639, 2021).
prostate adenocarcinoma (1 paper, 2025). "Survival analyses using TCGA data indicated that CYP4F3 lacked prognostic significance in prostate adenocarcinoma." (PMID 40723371, 2025).
cancer (18 papers, 2006 to 2025). A tumor composed of atypical neoplastic, often pleomorphic cells that invade other tissues. "Multiple studies report a correlation between the CYP4F3 splice variants and the development of cancer, immune disorders, and heart disease." (PMID 40858268, 2025). "In addition, there are limited studies for the gain and loss of function of CYP4F3 in different cancers distinguishing the isoforms CYP4F3A and CYP4F3B." (PMID 40858268, 2025). "The study provides a comprehensive approach to the expression, clinical relevance, and genetic variation of the CYP4B1, CYP4F12, and CYP4F3 genes in breast and other cancers." (PMID 40723371, 2025). "The CYP4B1, CYP4F12, and CYP4F3 overall survival (OS) analyses were conducted using the TIMER2.0 in pan-cancer." (PMID 40723371, 2025). "While the specific role of CYP4F3 in tumorigenesis remains unclear, its involvement in the metabolism of bioactive lipids and drugs points to it as a promising candidate in cancer research." (PMID 40723371, 2025). "However, the specific mechanisms of CYP4F3 in cancer onset, progression, and metastasis remain largely elusive." (PMID 38795162, 2024). "Elevated RNA expression of cytochrome monooxygenases (CYP4F11 and CYP4F3) and glutathione peroxidase 2 (GPX2), among others, was found in smoking-related malignancies that had minimal baseline leukocyte infiltration." (PMID 40723371, 2025). "CYP4B1, CYP4F12, and CYP4F3 gene expression levels were found to correlate with ESR1; then, a tumor versus normal tissue analysis and an overall survival evaluation in several types of cancer were conducted." (PMID 40723371, 2025). "miRNA–mRNA network analysis further indicated potential post-transcriptional regulatory mechanisms; collectively, these findings identified CYP4F3 as a negative prognostic biomarker and a potential therapeutic target in this type of cancer." (PMID 40723371, 2025). "Similarly, CYP4F3 and CYP20A1 were prominently expressed in advanced-stage HNSCC patient biopsies, indicating that the tumour microenvironment may upregulate these isoforms to support cancer progression." (PMID 41174467, 2025).
tumor (11 papers, 1971 to 2025). "•Identification of CYP4F3 as a potential biomarker for CRC prognosis based on its upregulation in tumor tissues and association with poor patient survival." (PMID 39106550, 2024). "Despite the low expression levels in endometrial tissue reported by the Human Protein Atlas, these findings implicate CYP4F3 in tumor progression and warrant further investigation to elucidate its functional role." (PMID 40723371, 2025). "This study identified the upregulation of CYP4F3 expression in colorectal cancer (CRC) and its association with poor patient prognosis through a comparative analysis between CRC tumor tissues with normal tissues from public databases." (PMID 39106550, 2024). "Ki67 intense immunostaining in CYP4F3 overexpression tumors suggests that CYP4F3 promotes tumor progression." (PMID 39106550, 2024). "Recent studies have shown the involvement of CYP4F3 in tumor development." (PMID 39106550, 2024). "Therefore, CYP4F3 plays a pivotal role in tumor development and progression through obstructing NRF2-mediated ferroptosis." (PMID 39106550, 2024). "Furthermore, CYP4F3 was identified as one of the 117 common genes up-regulated in cold tumors across smoking-related cancers, exerting dominance in immunoregulation and associated with NRF2 pathway activation and the tumor immune microenvironment." (PMID 39106550, 2024). "The overexpression of CYP4F3 enhanced the resistance of CRC cells to ferroptosis by upregulating NRF2 and promoted tumor proliferation and migration." (PMID 39106550, 2024). "The results indicated that the expression levels of (A) CYP4B1 and (B) CYP4F12 genes were higher (p < 0.05) in normal tissue than in tumor tissue, whereas (C) CYP4F3 expression levels were not significantly different." (PMID 40723371, 2025). "Furthermore, immunostaining of CYP4F3, Ki67, NRF2, and GPX4 were performed on the tumor tissues." (PMID 39106550, 2024).
CYP4F3 also shares sentences with these, for which no sentence is quoted: cardiovascular disease (3 papers); G6PD deficiency (3); Plasmodium vivax malaria (3); Allergy (2); asthma (2); dementia (2); hepatic insufficiency (2); hepatocellular carcinoma (2); Hypertension (2); Obesity (2); acute renal failure (1); atherosclerosis (1); attention deficit-hyperactivity disorder (1); bladder cancer (1); blastoma (1); breast tumors (1); chronic heart failure (1); Cirrhosis (1); COVID-19 (1); cystic fibrosis (1); endometriosis (1); epilepsy (1); glioma (1); Granuloma (1); Headache (1); Hearing impairment (1); heart disease (1); heart failure (1); hematologic malignancy (1); Hepatic steatosis (1).
A further 30 diseases each share a sentence with CYP4F3 in 1 paper.